CD4 (CD4 molecule)
Diseases named in the same sentence as CD4 in open-access papers (continued):
Sharing a sentence is not in itself a finding about the gene and the disease.
tumor (continued). "First, what breaks peripheral tolerance in self-reactive CD4+ T cells within the tumour microenvironment ?" (PMID 32457487, 2021). "The ability to create an immunosuppressive microenvironment by the tumor is further evidenced by the fact that CD4 lymphocytes infiltrating GIST have a higher expression of PD1 in comparison to lymphocytes from matched blood." (PMID 34298737, 2021). "This cross-reactivity of microbes with tumor antigens influences anti-cancer immunotherapy as well, as CD4+ and CD8+ T cells specific for microbial epitopes are necessary for the efficacy of anti-PD1 and anti-CTLA4 therapies." (PMID 33708214, 2021). "We found that those of the high infiltration cluster have a higher proportion of majority immune cells, such as CD8+, CD4+, and B cells, as well as macrophages, which usually act as the main initiator of immune responses against the primary tumor." (PMID 33815462, 2021). "This higher percentage of CD45+CD4+ cells was due to the injected tumor cells that expressed CD4+ cells." (PMID 34162832, 2021). "TILs are immune cells that are triggered by the host's immune response to the tumor; including T cells (CD4+ T helper lymphocytes/ Th, CD8+ cytotoxic T lymphocytes/ CTLs, and FOXP3+ regulatory T-cells/ Tregs), macrophages, dendritic cells, and mast cells." (PMID 34395318, 2021). "Conversely, an increase in tumor purity was positively correlated with the expression of CDK-1 in COAD due to CD4+cells and CDK-4 in COAD and READ resulting from a fraction of immune cells." (PMID 33732631, 2021). "The tumor microenvironment (TME) is closely associated with the response to ICB treatment, and the abundance of tumor-infiltrating CD4+T cells and CD8T+ cells are associated with the immune response." (PMID 34859010, 2021). "Three out of five mice showed complete regression of tumor in the B. longum 420 and IgG isotype control group, whereas all mice died from tumor growth in the B. longum 420 and anti-CD4 or anti-CD8 depletion antibody groups." (PMID 34589578, 2021). "CD4+ T cells play a key role in enhancing tumor control, both during effector T cell initiation and in the tumor microenvironment." (PMID 35095898, 2021). "Recent studies have confirmed the important role of tumor infiltrating lymphocytes (TILs) in tumor progression, which are mostly composed by T CD4+ and T CD8+." (PMID 33691674, 2021). "DCs are involved in tumor-antigen priming and represent TAAs conjugated with class-I human leukocyte antigens (HLA) to activate CD4+ T helper cells and B cells." (PMID 34485117, 2021). "Additional therapeutic targets suitable for boosting anti-tumor effector responses have been found inside effector CD4+ and CD8+ T cells." (PMID 34073258, 2021). "There is a distinct methylation signature of the tumor infiltrating CD4+ T cells compared to CD4+ T cells from blood from the same patient." (PMID 34012510, 2021). "Simultaneous Treg downregulation and tumor specific CD4 and CD8 T cell expansion with increased PD-1 expression peak 14 days after ablation in IRE treated PDAC patients." (PMID 34359801, 2021). "Abnormal immune activation of Langerhans and CD4+ cells has been showed as the potential mechanism for the deterioration of tumor control in carcinomas in chronic arsenic exposure." (PMID 34198922, 2021). "It has been shown that membrane-bound Hsp70 serves as a tumor-specific antigen readily recognized by both NK cells and cytotoxic CD4+CD25+ T-lymphocytes." (PMID 34206968, 2021). "In murine models of breast cancer, blocking CSF1/CSF1R signalling inhibited TAM recruitment and delayed tumour regrowth following RT (5 Gy), an effect associated with an increase in CD8+ T cells and a reduction in CD4+ (helper) T cells." (PMID 33467153, 2021). "This is made up of regulatory T cells (CD4+CD25+FOXP3+), tumor-associated macrophages (TAMs) and myeloid-derived suppressor cells (MDSCs), as well as other stromal cells such as GSC-derived pericytes." (PMID 34771532, 2021).
tumor (continued). "In the last 5 years, many reports have recognized the critical role of CD4+ T cells in driving anti-tumor immunity and supporting anti-tumor CD8+ T cell responses." (PMID 34502169, 2021). "Epigenetics also control the expression of immune checkpoints, thus regulating tumor reactive CD4+ T cells exhaustion." (PMID 34262562, 2021). "Tumors with CTSS alterations were characterized by a remodeled tumor-prone microenvironment with an increased infiltration of CD4+ T cells while limiting CD8+ T cells recruitment." (PMID 34335584, 2021). "A major difference between recognition of tumor cells by CD4+ T cells and CD8+ CTLs cells is that the latter detect antigens presented by MHC I complexes." (PMID 34135885, 2021). "The presence of both tumor-specific CD4+ and CD8+ αβT cells has been reported to significantly improve clinical responses compared to tumor-specific CD8+ αβT cells alone." (PMID 34759930, 2021). "According to our previous data, the Tag7 protein expressed on the surface of cytotoxic CD4+ T-Lymphocytes can interact with Hsp70 on the membranes of tumor cells." (PMID 34206968, 2021). "We adapted a previously established T-cell library approach to estimate the frequency and isolate in an HLA-independent manner tumor-specific CD4 T cells in a high-throughput manner." (PMID 34064410, 2021). "This concept did not only allow to select for highly tumor-reactive γδTCR, but also within the context of Vδ2+ TCRs to reprogram both CD4+ and CD8+ αβT cells." (PMID 34759930, 2021). "B cells can restrict tumor growth through phagocytosis by macrophages, facilitating tumor killing by NK cells, generating tumor-reactive antibodies, and the priming of CD4+ and CD8+ T cells." (PMID 33670230, 2021). "This suggested that personalized vaccines can be made using algorithms that select mutations from a patient’s mutanome that have the highest probability of creating widely expressed tumor antigens to induce a CD4+ response." (PMID 34885150, 2021). "CD4 + Th cells target tumor cells either directly through cytolytic mechanisms or indirectly by modulating the tumor microenvironment (TME)." (PMID 34222240, 2021). "Staining showed CD4+ and CD8+ T cells to be scattered throughout the tumor region (respectively) however, significantly increased numbers of CD4+ T cells were apparent in the Gsk3b cKO sections as determined using Imagescope software." (PMID 34142056, 2021). "The numbers of CD4 T cells in the tumor microenvironment are related to the efficacy of PD-1 therapy." (PMID 34447697, 2021). "In general, TAMs exert an inhibitory effect on the anti-tumor immune response and engage in bidirectional interactions with other cells, such as CD4+ and CD8+ T cells." (PMID 33918618, 2021). "This latter finding implicates the potential involvement of CD4+ TILs, more likely to be CD4+ Tregs, in promoting tumor angiogenesis." (PMID 33916009, 2021). "Other observations noted in the three models were as follows: increased tumor-infiltrating CD4 and CD8 cells, lower MDSC populations in TILs, and increased CD8+ IFN-γ+ cells compared to the Ig control." (PMID 34282763, 2021). "In particular, the CD4+ regulatory T cells (Tregs) expressing the transcription factor Foxp3 are highly immune suppressive and promote tumour progression by suppressing effective anti-tumour immunity." (PMID 33451015, 2021). "Our results also found that activated immune cells were mainly enriched in tumor tissues, for instance the activated memory CD4+ T cell, while naive cells, such as naive B cells, were more abundant in the normal tissue than in tumor tissues." (PMID 33816503, 2021). "Taken together, Chinese medicine compounds control tumor growth by modulating the differentiation of CD4+ T cells, enhancing Th1 immune response as well as restraining the function of Th2 and Th17." (PMID 34722304, 2021).
tumor (continued). "Associated with reduction of tumor progression and fibrosis by DMHCA were its inhibitory effects on MDSC infiltration coincident and an increased percentage of CD4 and CD8 effector T cells." (PMID 33780491, 2021). "Given the role of EZH2 in early CD4+ T cell differentiation, its targeting should be further investigated as a strategy to modulate CD4+ T cell responses during tumor immunity." (PMID 33859645, 2021). "Tumor-infiltrating LY6G MDSCs from orthotopic liver tumors treated with sorafenib significantly induced CD4+T cells expressing IL-10 and TGF-β and down-regulated the cytotoxic activity of CD8 T cells." (PMID 34869376, 2021). "In this study, we assessed the effect of concurrent CRT on peripheral tumor-specific CD4 Th1 response and immunosuppressive cells in patients with lung or head and neck cancer." (PMID 34144673, 2021). "CD4+ T cells can directly eliminate tumor cells through cytolysis or indirectly regulate the TME to target tumor cells." (PMID 33894748, 2021). "Mature DCs stimulated by tumor-associated antigens can promote the proliferation and activation of CD8+ and CD4+ T lymphocytes." (PMID 34801032, 2021). "(B) Representative plots (left) and statistical analysis (mean ± SEM) of gated CD44+ CD4+ tumor-infiltrating lymphocytes (TILs) analyzed for puromycin incorporation." (PMID 34787568, 2021). "Further study showed that IL-36γ-OV increased the number of tumor antigen-specific CD4+ and CD8+ T cells and the therapeutic efficacy depended on both CD8+ and CD4+ T cells." (PMID 33538860, 2021). "In line with it, an independent study demonstrates that MDSCs from tumour-bearing mice compromise TGFβ-induced Foxp3+CD4+CD25+ Treg differentiation in a ROS-dependent manner." (PMID 33941245, 2021). "Cytokine array profiling revealed that resistant tumors had increased infiltration of Th17 CD4+ T cells, which secrete the tumor-promoting cytokines IL-17 and IL-2216." (PMID 33972557, 2021). "Intratumoral CD4+ T cells are increasingly recognized as responsible for antitumor immune response and the production of inflammatory mediators that induce tumor growth, invasion, angiogenesis, and metastasis which are associated with clinical outcomes." (PMID 33301062, 2021). "When it comes to a variety of T cells, as the key component of the anti-tumor immune response, tumor-infiltrating lymphocytes represented by CD4+ Th cells and CD8+ CTLs are only present in remarkably low numbers in the CNS." (PMID 33917399, 2021). "Tumor infiltrating lymphocytes were identified using CD45 staining as well as further differentiated through CD4 and CD8 marking." (PMID 33953302, 2021). "In particular, the activation of CD8+ Teffector or CD4+ Thelper cells was shown to be suppressed by tumor-derived sEVs, e.g., upon targeting antigen-presenting dendritic cells (DC), thus impairing lymphocyte activation and survival." (PMID 34503190, 2021). "Tumor neoepitope-reactive CD4+ T cells were crucially involved in generation of potent anti-tumor CD8+ T cell responses." (PMID 35097027, 2021). "Vγ9Vδ2TCR and CD8αβ-independent αβTCRs have been also reported to reprogram CD4+ T cells, which not only have the ability to exert tumor cell killing but also induce maturation of professional antigen-presenting cells." (PMID 34759930, 2021). "In draining lymph nodes (dLNs), there was a small percentage of GPR171-positive T cells, which were presumably tumor-reactive T cells; over half of intratumoral T cells, including both CD4+ and CD8+ T-cell subsets, expressed GPR171." (PMID 34615877, 2021). "The number of T helper cells, promoting tumor growth under the influence of the TME (CD4+), was significantly increased under Bevacizumab as compared to Doxorubicin (p = 0.005)." (PMID 33401528, 2021).
tumor (continued). "Our studies identified a mechanism by which Mmp2 modulates antitumor activity: ligation of TLR2/4 on APCs promotes tumor infiltration of myelosuppressive populations while reducing tumor infiltrating CD4+ and CD8+ T cells, NK cells, and CD103+ DCs." (PMID 34032639, 2021). "The reason is that PD-1+ FoxP3high CD45RA− CD4+ T (effector Treg) cells infiltrate the tumor and inhibit effector T cell activity." (PMID 33946835, 2021). "In particular, the anti-tumor effects mediated by CD4+ T cells and CD8+ cytotoxic T lymphocytes have been well documented." (PMID 33495451, 2021). "For example, the proportion of resting memory CD4+ T cells was high in the tumor group, while plasma cells and CD8+ T cells have a higher proportion in the normal group." (PMID 34950700, 2021). "In contrast, therapy-treated DIO mice exhibited progressive tumor outgrowth and blunted T cell responses, characterized by reduced intratumoral frequencies of IFNγ+ CD4+ and CD8+ T cells." (PMID 34064933, 2021). "Re‐stimulation of isolated splenic CD4+ T cells with tumour antigens dramatically induced the secretion of the Th1 cytokine IFN‐γ in the group immunized with tEV plus SyBV." (PMID 34262675, 2021). "The Treg cells, a subpopulation of CD4+ helper T cells, can facilitate the tumor progression by suppressing the antitumor immune responses of the host." (PMID 34778292, 2021). "In contrast, sequential administration of the OX40 agonist and anti-PD1 facilitated tumor elimination, which was dependent on CD4+ and CD8+ T cell responses." (PMID 33747948, 2021). "A second study using a different HER2/neu derived peptide, showed similar results with an increased presence of CD4+ tumour-infiltrating lymphocytes as well." (PMID 34276688, 2021). "Depletion of CD8+ and CD4+ T cells induces tumors to come out of dormancy and apoptosis and induces an increase in tumor cell Ki67, which increases their proliferation and activation." (PMID 33869189, 2021). "ZSTK474 treatment significantly inhibited tumor growth, but depletion of either CD4+ T cells or CD8+ T cells abrogated the antitumor effects of ZSTK474, indicating that both CD4+ T cells and CD8+ T cells contribute to tumor growth inhibition by ZSTK474." (PMID 34446575, 2021). "Overall, after anti-PD-1 exposure, the distribution of immune cells in the tumor microenvironment was predominantly composed of CD4+ T lymphocytes and was generally poor in CD8+ T cells." (PMID 34771650, 2021). "In early mouse experiments, the adoptive transfer of in vitro expanded tumor antigen-primed T effector cells showed that CD4+ T cells are needed to augment CD8+ T effector responses." (PMID 33546283, 2021). "Other studies also indicate the infiltration of lymphocytes, including CD4/8+ T cells and NK cells to the site of tumor after Salmonella infection." (PMID 33717106, 2021). "For example, RANK/RANKL interactions with CD4+ T cells and breast cancer cells promotes invasion and dissemination of tumor cells and the formation of bone metastases." (PMID 34204474, 2021). "The core genes of this prognostic model were subsequently confirmed to have a significant correlation with B lymphocytes and CD4+ T cells infiltrated in HCC tumor tissue." (PMID 34324544, 2021). "For analyzing ESR2 expression level versus T cell infiltration in each tumor, the total expression of CD4, CD8α, GZMB (log2 counts per million) was used to assess the infiltration of cytotoxic T-lymphocytes, and correlations were computed vs ESR2 expression." (PMID 33462142, 2021). "Further analysis of T cell markers revealed, that the CD4+ helper T cell marker message levels were slightly increased in both tumor types along with the regulatory T cell marker FOXP3." (PMID 35366268, 2021). "In contrast, MTR-OralGem administration increased the frequencies of tumor-infiltrating CD3+CD4+ and CD3+CD8+ T cells compared to MTD-Gem-treated mice, and T effector cells reached levels similar to those of the control group." (PMID 33920884, 2021).
tumor (continued). "Although the suppressive role of CD8+ cells in tumor development is quite clear, CD4+ cells can interact dually and convert from anti-tumor to pro-tumor role." (PMID 33804155, 2021). "By compartmentalized analysis, an increase in CD4+ T cells at the tumor infiltrative margins, as well as of CD8+ T cells at the tumor core, was noted in post-vaccination specimens rather than in baseline biopsies." (PMID 34831389, 2021). "In contrast, increased levels of tumor-infiltrating lymphocytes (TLS), such as CD4+ T cells and CD8+ T cells, are associated with elevated survival rates and tumor responsiveness." (PMID 34457003, 2021). "These and other studies reflect the importance of CD4+ T cell responses in the tumor microenvironment (TME)." (PMID 33777008, 2021). "The tumor-infiltrating lymphocytes primarily consisted of CD4+ T-cells with a very small percentage of CD8+ T-cells." (PMID 34944945, 2021). "By contrast, during tumor progression there is a subversion of macrophage functions, from M1 to M2, due to many factors, including the presence of IL-4 synthesized by CD4+ T cells and tumor cells and of tumor-derived GF such as CSF1 and GM-CSF." (PMID 33920505, 2021). "In tumor-free mice, PD-1 expression was comparable between AMPK-deficient CD4+ T cells and WT CD4+ T cells." (PMID 34649584, 2021). "Tumor-infiltrating CD4+, CD8+ T cells, and NK cells in patients with HCC have been found to be functionally compromised, and the low CD4+ and CD8+ TIL counts have been found to predict extremely poor HCC-specific survival." (PMID 33710817, 2021). "When patients progressed to HCC, CD4+ T lymphocytes were redistributed in tumor tissue, with CD4+ TILs expression in the peritumoral area being greater than that in the intratumoral area." (PMID 34566989, 2021). "Four prognostic‐related tumor‐infiltrating immune cells, including T cells CD4 memory resting, Macrophages M1, and Macrophages M2 were revealed." (PMID 34598322, 2021). "CD4+ Th17 cells, γδ+ T cells, and innate lymphoid cells (ILCs) represent the major sources of IL-17 in the tumor microenvironment in the gut15." (PMID 33893298, 2021). "Overexpression of DDR1 promotes tumor cell proliferation (including regulating tumor-infiltrating CD4 + and CD8 + T cells), while silencing or knocking out DDR1 can reduce tumor cell growth." (PMID 34805157, 2021). "Group2 had the highest immune scores and the lowest tumor purity scores; higher proportion of T cells CD4 memory activated and M1 macrophages; and higher expression of six immune checkpoints and three hub genes." (PMID 34893051, 2021). "Tumor-associated exosomes from different cancer types were shown to modulate T cell function and were shown to suppress CD8 as well as CD4 T cells derived from normal donor PBLs." (PMID 34831378, 2021). "More importantly, these studies support the concept that both MHC-I– and MHC-II–restricted neoantigens need to be processed and presented by APCs, indicating that APCs shape anti-tumor immunity by coordinating the collaboration of CD4 and CD8 T cells." (PMID 34290401, 2021). "High expression of both markers was confirmed in isolated CD4+ T cells from the lesion of a patient in the tumor stage." (PMID 34220814, 2021). "Related results indicated Mn2+ treatment induced a significantly increased CD8+ and CD4+ TILs (tumor-infiltrating lymphocytes, TILs) in diverse tumor models to reduce tumor burdens." (PMID 34956229, 2021). "TMZ monotherapy increased tumor infiltration of CD4+ and CD8+ T-cells in the Nhe1 Con mice by ~ 2-fold, but, not in the Nhe1 KO mice." (PMID 33391535, 2021). "LN LECs can also cross-present tumor antigens to promote CD4 suppression and produce immunosuppressive molecules such as nitric oxide, TGF-β, and IDO to promote an immunosuppressive nodal microenvironment." (PMID 34241649, 2021). "Various CD4+ lineages can orchestrate a broad range of effector activities during the initiation, expansion, and memory phase of endogenous anti-tumor immune response." (PMID 34012510, 2021).